IL6 (interleukin 6)
Diseases named in the same sentence as IL6 in open-access papers (continued):
Sharing a sentence is not in itself a finding about the gene and the disease.
infection (continued). "Moreover, it rapidly reduced the expression of IL-10 in the later stage with the decline of IL-1β, IL-6, TNF-α, and IFN-γ, to prevent the continuously excessive release of IL-10 from causing severe immune suppression and uncontrollable infection." (PMID 35071595, 2022). "Infected macrophages serve as a possible reservoir for CHIKV and may contribute to the persistent inflammation driven by secretion of cytokines (e.g., IL-6, CCL2) and joint pain associated with infection." (PMID 36078125, 2022). "However, the expression levels of IL-1β and IL-6 were decreased by SP600125 treatment in monocytes or macrophages in the presence of CHa strain infection." (PMID 35837399, 2022). "Similarly, ESBL-EAEC infection elevated transcription levels of IL-1β, IL-6 and TNF-α in colonic tissues, but recovered after GA administration with an obvious decline of IL-10 and TGF-β." (PMID 35399688, 2022). "IL-6 affected infection outcomes in mice and exerted a protective role, primarily via macrophages." (PMID 35297653, 2022). "In addition, IL-6 has been reported to play an important role in response to infection, hematopoiesis, and immune activation." (PMID 35392889, 2022). "The cleavge-Caspase3 and IL-6 protein expression rose as infection time increased, peaking at 12 h." (PMID 35812882, 2022). "Interleukin-6 (IL-6) was induced in a minor population of DDIT3high cells after infection." (PMID 35038898, 2022). "This is unlikely coincidental and most likely indicates that at this stage of infection, IL6 production causes little to no harm for virus, and therefore, suppression of IL6 production becomes not essential." (PMID 36379254, 2022). "IL-6 is rapidly produced in response to tissue injury and infection and promotes host immunity by stimulating acute phase responses and immune reactivity, while imbalanced IL-6 synthesis contributes to the pathological effects on chronic inflammation and immune action." (PMID 36145301, 2022). "Furthermore, at the protein level, we also confirmed that all four Th2 cytokines (IL-4, IL-6, IL-10, and IL-13) were progressively enhanced in both mouse and rat lungs during the late infection phase of AC." (PMID 35617354, 2022). "Besides estrogen, treatment with proinflammatory cytokines such as interleukin 6 (IL-6) and tumor necrosis factor alpha (TNFα) and infection with RNA viruses also induce the upregulation of RNF115 in various cell lines and primary human and mouse cells." (PMID 35844553, 2022). "By the sixth day after infection, IL-6 and TNF-mRNA levels in the brain had increased by 300-fold." (PMID 35215199, 2022). "IL-6 is a prototypical cytokine that has redundant and pleiotropic activity, the synthesis of which is promptly induced to aid in host defense when tissue damage or inflammation because of infections or injuries occurs." (PMID 36467730, 2022). "In-vitro and animal studies have shown that infection of neutrophils with Coxsackievirus B3, a prevalent enterovirus, triggers the release of tumor necrosis factor-alpha, interleukin-6, and other cytokines, which mediate inflammation and enhance neutrophil survival." (PMID 36337784, 2022). "During the acute stage of infection, both IL-6 and IL-1β are known to be expressed." (PMID 35531475, 2022). "IL‐6 expression is tightly regulated at the transcriptional level to ensure physiological fluctuations in IL‐6 during homeostasis and rapid induction during infection, trauma or injury." (PMID 34618359, 2022). "Indicators such as white blood cell count, CRP, PCT, IL-6, and albumin may reflect the state of the body after infection to varying degrees." (PMID 36237437, 2022). "Panc47 FAK-wt cells were transduced using lentiviral infection with plasmids encoding shRNA targeting IL6 or a control non-targeting shRNA." (PMID 36138073, 2022). "We found higher concentrations of TNF-α and IL-6 in the acute phase of infection." (PMID 35456119, 2022).
infection (continued). "Typically, the elevation of serum IL-6 associated with CRS occurs within 3 weeks after CAR-T cell infusion, so the “double peaks of IL-6” is identified as one of the characteristics of life-threatening infections." (PMID 35757715, 2022). "Measurement of viral ORF1A RNA by reverse transcription quantitative PCR (RT-qPCR) was used to assess the levels of viral transcripts 24 and 48 hours after infection, whereas IL6 and IFNB1 mRNA levels were measured to assess the concomitant induction of cytokines." (PMID 36264642, 2022). "Similarly, E. coli 1587 infection elevated the transcription levels of IL-1β, IL-6, TNF-α, and IL-10 in the colonic tissues, while TGF-β was decreased." (PMID 35643532, 2022). "The result showed that the expression of il-6 was significantly promoted at 6 h after infection and then reduced to a lower level at 16 h after infection; the level at 48, 72, and 96 h after infection were almost the same low as that at 6 and 96 h without infection." (PMID 36059498, 2022). "Il-6 and IL-10 can be used as indicators of anti-infection treatment effects." (PMID 35432366, 2022). "The higher the IL-1β and IL-6 levels, the more serious the infection." (PMID 35531475, 2022). "IL-6 is mainly produced by macrophages, T lymphocytes and B lymphocytes, and can be induced by a variety of cytokines such as viruses, endotoxins and tumor necrosis factors in tissue damage or infection." (PMID 35711907, 2022). "Similarly, the mRNA expression levels of IL-6 and iNOS in jejunum were obviously up-regulated in S. enteritidis-alone infection group (p < 0.01)." (PMID 36613296, 2022). "It appeared that IL-6 deficiency in B cells leads to a general down-regulation of the ifng gene expression in the lung and a decreased frequency of mycobacteria-specific CD4+IFN-γ+ T cells at the early stage of infection." (PMID 35154093, 2022). "Significantly lower interleukin 6 (IL-6) and keratinocyte-derived chemokine (KC) levels were found in the Δpsmα infected mice compared with both WT and Δpsmβ infected mice on day 3 after infection." (PMID 36065015, 2022). "The study further examined different key immune genes such as the transcript level of tumor necrosis factor-alpha (TNFα), interleukin-6 (IL-6), interleukin-8 (IL-8), interleukin-10 (IL-10), interleukin-1 beta (IL-1β), and transforming growth factor-beta 1 (TGFβ1) during the early phase of infection." (PMID 36145441, 2022). "Elevated CRP (30.6 mg/L) and interleukin-6 (19.33 pg/mL) levels suggested an acute-phase infection." (PMID 36211956, 2022). "IL-6 can regulate the growth and differentiation of various cells, immune responses, acute responses, and hematopoietic functions, and it plays an important role in the body’s anti-infection immune response." (PMID 35805814, 2022). "While IL-1β and TNF-α levels may drop within 24–48 h, elevated IL-6 levels persist for a longer period over the course of the infection." (PMID 35888173, 2022). "On a molecular level, it has been shown that during infection, inflammatory markers like interleukin-6 (IL-6) prolong ventricular myocyte action potential by inhibiting the hERG potassium channel in cardiac myocytes, providing a direct mechanistic link between QTc prolongation and inflammation." (PMID 35811700, 2022). "After infected with Yersinia pseudotuberculosis, the highest infection-induced immunomodulatory genes were those of the major proinflammatory cytokines: interleukin-1 alpha (il1a), interleukin-1 beta (il1b), interleukin-6 (il6), interleukin-17F (il17f) and interferon gamma (ifng)." (PMID 36059501, 2022). "IL-6 increases in the effluent of patients with acute bacterial peritonitis and may be used to evaluate the bacterial clearance during the infection." (PMID 35563220, 2022). "We next confirmed whether infection of cells with SARS-CoV-2 also induces upregulation of IL-6 and IL-8." (PMID 36177032, 2022). "IL-6 is a transient cytokine secreted in response to infection and injury." (PMID 35974048, 2022).
infection (continued). "IL-6 expression levels are abnormally elevated during infection." (PMID 35463642, 2022). "Additionally, ELISA showed that the levels of secreted pro-inflammatory cytokines IL-1β and IL-6 were significantly increased in the mice of the ‘Scald + Infection’ group compared with those of the ‘Sham + Infection’ group." (PMID 34898366, 2022). "Because IL-6 increases viral cell entrance and multiplication, it may be an excellent predictor of death before infection." (PMID 35573503, 2022). "However, the secretion level of IL-6 in the coinfection group restored and was dramatically higher than that in the coaggregation group at 48 h of infection." (PMID 35573793, 2022). "According to the results of this study, COX2 and IL-6 are involved in the infection." (PMID 35145559, 2022). "Consistent with data from transcriptome analysis Gbl7n, Gbl11n, Gbl13n, Gbl17n, and Gbl25n cells also largely expressed IL-6 pro-inflammatory cytokine in response to MV, while the infection exerted significantly lower levels of IL-6 production in Gbl12n, Gbl16n, and Gbl24n cells." (PMID 36366531, 2022). "The infection of A549 and SK-OV-3 with HAdV26 induced changes in the expression of the IL-6, IL-8, IL-1β, and TNF-α genes; namely the expression of all four genes was increased in HAdV26-infected A549 cells, while HAdV26 infection resulted in increased expression of IL-6 and TNF-α in SK-OV-3 cells." (PMID 35458402, 2022). "Cytokine analysis of blood plasma samples collected 4 hours after infection revealed an increase in concentrations of IL-1α, IL-6, the CXC chemokine KC, G-CSF, MCP-1, and the CC chemokine eotaxin in WT but not in Trpm5–/– mice compared with concentrations before infection." (PMID 35503420, 2022). "IL-6 is produced in response to infection as well as in tissue damage." (PMID 36294967, 2022). "Measurably increased IL-6 levels have been noted following trauma, stress, and infection." (PMID 35204599, 2022). "Thus, we measured IFNβ, IL-6 and TNFα cytokine production at 24 hours post-infection in both female and male WT and Nlrx1-/- BMDMs infected with LgyLRV1+ parasites or stimulated with poly I:C." (PMID 35651602, 2022). "IL-6 is known to be secreted by phagocytes following their interaction with exogenous pathogens and while repairing tissue damage resulting from either trauma or infection." (PMID 36091045, 2022). "It was implied that IL6 may have a vital effect on the infection and pathogenesis and can be used as a key starting point for prediction and treatment." (PMID 35165525, 2022). "NOTCH activation might cause an increase in SARS-CoV-2 cell entry and infection, exacerbate inflammation in a NOTCH : IL-6 positive feedback loop, and inhibit functional airway regeneration." (PMID 35992174, 2022). "Interestingly, duRIG-I-CARD- or full-length duRIG-I- (DTMUV infection) mediated pro-inflammatory cytokines (IL-1β, IL-2, IL-6, IL-8) expression level was significantly promoted by overexpression of duLGP2." (PMID 35784309, 2022). "Up‐regulation of IL‐6 can be induced by infection of many viruses including SARS‐CoV." (PMID 35426250, 2022). "Considering their effects during pregnancy, luteolin and kaempferol inhibited infection-induced inflammation in gestational tissues by reducing proinflammatory cytokines (IL-6 and IL-8) and prostaglandins (PGE2 and PGF2α) expression, indicating their potential therapeutic effect for preterm birth." (PMID 36339549, 2022). "Particularly, IL-6, IL-10, and IL-8 can serve as predictive markers of infection." (PMID 35463642, 2022). "Moreover, SEP attenuated the MPO level in the lung and inflammatory cytokines IL-1β, TNF-α, IL-6 in the peritoneal macrophage during infection." (PMID 35370674, 2022). "Infection of respiratory epithelial cells by hRSV results in high expression of pro-inflammatory factors such as IL6, which may play a relevant role in the pathogenesis of hRSV in the lungs of infected infants, as well as Rag2−/− mice." (PMID 36016362, 2022).
infection (continued). "Inflammation is associated with the release of proinflammatory cytokines, such as tumor necrosis factor α (TNF‐α), interleukin 1 (IL‐1), and interleukin 6 (IL‐6), which aid in the recruitment of immune cells (such as neutrophils) to the site of injury or infection." (PMID 35315122, 2022). "Multiplexed detections of CRP, PCT, and IL-6 can cover the whole period of infection." (PMID 35144683, 2022). "Infection by severe acute respiratory syndrome coronavirus 2 (SARS‐CoV‐2) can trigger excessive interleukin (IL)‐6 signalling, leading to a myriad of biological effects including a cytokine storm that contributes to multiple organ failure in severe coronavirus disease 2019 (COVID‐19)." (PMID 35426250, 2022). "We reasoned that this partial resistance to N67C infections may be due to an insufficient early IFN‐α/β treatment or an incomplete blockage of IL‐6 signaling." (PMID 35635376, 2022). "Interleukin-6 (IL-6), a multipotent cytokine widely distributed in the human body, is involved in the growth and differentiation of a variety of cells and plays a vital role in the body’s acute phase response and immune response against infection." (PMID 36325329, 2022). "Following this result, we hypothesized that the lack of efficacy of prophylactic anti IL-6 treatment in preventing severe SFTS could be due to critical antiviral functions of IL-6 during the early stages of infection." (PMID 35529317, 2022). "IL-6 has both pro-inflammatory and anti-inflammatory activities, while chemokine eotaxin-1 plays a role in parasite-induced inflammation by mediating mobilization, recruitment, and proliferation of primary eosinophils to the site of infection." (PMID 35603171, 2022). "The infection with the influenza virus causes acute inflammation via a direct invasion into the CNS, resulting in the excessive production and action of proinflammatory cytokines including TNF-α and interleukin (IL)-6." (PMID 35326323, 2022). "Interestingly, the IAV infection followed by secondary SARS-CoV-2 infection showed negligible increases of inflammatory cytokines in BALF compared with the IAV single-infection group (except IL-6; 10 dpi)." (PMID 35107382, 2022). "Infection of airway epithelial cells by SARS-CoV-2 causes cytological damage by activating the local immune response, releasing proinflammatory mediators such as IFNγ, IL-1β, IL-6, TNF-α." (PMID 36012968, 2022). "IL-6 binds to its soluble receptor to trigger monocytes’ differentiation into macrophages, which facilitates the recruitment of the immune components to the site of infection with concomitant inflammation." (PMID 36423150, 2022). "Consistent with this hypothesis, after infection with ΔKapB, IL-6 transcript levels were much reduced relative to that observed with WT infection." (PMID 34936820, 2022). "To identify potential cytokine‐production patterns in WT and KO mice in response to N67C or YM infection, we infected WT, Ifih1–/–, Mavs–/–, Mb21d1–/–, and Tmem173gt mice with either N67C or YM, then examined the serum amounts of IFN‐α, IFN‐β, and IL‐6 during the course of each infection." (PMID 35635376, 2022). "During NiV infection, epithelial cells and type II pneumocytes from the bronchiole are the primary targets and infection induces the production of inflammatory cytokines such as IL-6, IL-8, IL-1α and granulocyte-colony stimulating factor (G-CSF), responsible for the recruitment of immune cells." (PMID 35632678, 2022). "This study using a large dataset demonstrated that the concurrent examination of CRP and IL-6 or PCT could be helpful for the early suspicion of infection, but careful interpretation is important because of their discrepancies." (PMID 36555941, 2022). "Furthermore, the expression of Smh1 led to reduced induction of IL-8, IL-6 and TNFα transcript upon infection, which was also observed to a weaker extent in uninfected cells." (PMID 36411449, 2022).
infection (continued). "IL-6 is an Inflammatory cytokine secreted by immune cells in tissue damage or infection conditions." (PMID 35361818, 2022). "This ratio in the il6 gene expression was retained at least up to week 7 post infection, although the overall expression level significantly decreased by this time point, despite substantial growth of the lung B-cell content, which also partially depended upon B-cell-provided IL-6." (PMID 35154093, 2022). "Both type I IFN responses and IL‐6 were abrogated by blocking infection using ACE2 antibodies." (PMID 35099061, 2022). "Persistently high levels of IL-6 during the recovery phase of the infection may contribute to impaired left ventricular function." (PMID 35888173, 2022). "According to the present study, the pathogenesis of osteomyelitis of the jaw—which is known to be induced by a mixed infection, where bone resorption and osteosclerotic lesions are combined—is mediated at least in part by the activation of IL-6 and p38 signaling." (PMID 36293485, 2022). "This may be a consequence of infection-induced immunosuppression and/or the use of steroids and/or interleukin 6 (IL-6) blockade to limit tissue damage." (PMID 35231086, 2022). "Similarly, increased IL-6 mRNA concentrations were seen in experimental rodent infections with BoDV-1." (PMID 35788177, 2022). "Moreover, the percentages of CD11b+Ly6ChiLy6G– cells were much lower in Tmem173gt, Mb21d1–/–, Myd88–/–, and Mavs–/–Il6–/– mice than in WT and Mavs–/– mice at day five after N67C infection." (PMID 35635376, 2022). "To find out whether the conditioned IL-6 knockout influences TB pathogenesis, we assessed lung histopathology in B-IL-6KO and WT mice at weeks 3 and 7 post infection." (PMID 35154093, 2022). "Moreover, during infection, there is an increase in proinflammatory cytokines (interleukin (IL)-1α, IL-1β, IL-6, IL-8, IL-18, tumor necrosis factor (TNF)-α, IFN-γ, leading to a disbalance in immune surveillance mechanisms and changes in the tissue environment." (PMID 36294658, 2022). "Taken together, our results clearly indicate that the most prominent role of B-cell-derived IL-6 in anti-TB response concerns the early phase of infection – more precisely, the third week of its development – when the host starts switching on a plethora of acquired immune reactions." (PMID 35154093, 2022). "Finally, we evaluated the potency of Regdanvimab and Sotrovimab to decrease the presence of pro-inflammatory cytokines like IL-6 during SARS-CoV-2 Delta or BA.1 infection." (PMID 36250084, 2022). "In the case of IL-6, it is thought that this pro-inflammatory cytokine could be part of an innate inflammatory response that precedes an adaptive response in natural infection, including SARS-CoV-2 infection." (PMID 36052060, 2022). "This hypothesis could explain IL-5, IL-1, IL-6, and IL-18 increased expression in the spleen after 2 weeks of infection following the upregulation in the intestine." (PMID 36187827, 2022). "Thus, the increase is primarily due to the inflammation associated with the infection as supported by a similar increase in the acute phase proteins CRP and IL-6 in this study and related ones." (PMID 35113876, 2022). "This discrepancy of IL-6 protein expression in these two studies may be the results of different infection time and different sample collections." (PMID 35694317, 2022). "In addition, TgPrx1KO and TgPrx3KO induced high levels of interferon gamma (IFN-γ) in infected mice at 8 days post infection, and increased IL-6 and IL-12p40 production from murine macrophages cultivated in vitro." (PMID 35328497, 2022). "IL6 has pro-inflammatory and anti-inflammatory properties, and it contributes to liver homeostasis by regulating metabolic function, regeneration, and anti-infection defense." (PMID 36611736, 2022). "In terms of H. pylori infection, it is well documented that this infection is associated with higher levels of IL-6 independent of the studied tissue or sample." (PMID 35884067, 2022).